MTOR (mechanistic target of rapamycin kinase)
Diseases named in the same sentence as MTOR in open-access papers (continued):
Sharing a sentence is not in itself a finding about the gene and the disease.
cancer (continued). "Cancers may show high mTOR pathway activity without an associated genetic or genomic alteration of canonical RTK/PI3K/AKT/mTOR pathway." (PMID 29362480, 2018). "Hence inhibition of mTORC through rapalogues or second-generation mTOR inhibitor ATP mimetics may have a beneficial impact on cancer through blocking this pathway." (PMID 30096787, 2018). "Since cancer cells with high eIF4E expression demonstrate resistance to the anti-proliferative effects of asTORi, combining dual mTORC1 and 2 inhibitors with HSV1-dICP0 could potentially provide the selective advantage of increasing viral oncolysis of mTOR-inhibitor resistant cancer cells." (PMID 30138450, 2018). "One approach to specifically interfere with cancer cell glucose and energy metabolisms involves the application of the anti-diabetic biguanides metformin and phenformin that exhibit anti-cancer properties by interfering with mTOR signaling and inhibiting mitochondrial complex I." (PMID 29794999, 2018). "Although our analyses of tumor responses and overall survival are based on very small groups and should be interpreted with the greatest caution, they could suggest that combining an mTOR inhibitor and a biguanide has anti-cancer activity in patients with advanced cancer." (PMID 28616837, 2018). "In cancer cells, a gene expressed only in the brain, carnitine palmitoyltransferase 1C, was reported to promote fatty acid oxidation and cell survival, and confer rapamycin resistance, indicating that this gene may act in parallel to mTOR-enhanced glycolysis." (PMID 30347859, 2018). "In this review, we survey the recent contributions of TSC physiopathology studies to understand the role of mTOR signaling in both neurogenesis and tumorigenesis and discuss how these new insights can contribute to developing new therapeutic strategies for neurological diseases and cancer." (PMID 29772672, 2018). "As reported by Khuri colleagues, mTOR inhibition triggers rapid and sustained activation of the PI3K/Akt survival pathway in the human lung and other types of cancer cells; therefore, the combination of mTOR-targeted therapy with drugs that block PI3K/Akt activation might also be reasonable." (PMID 30087612, 2018). "We could not find the association of mTOR inhibitors use and risk of de novo cancer development or mortality in patients with kidney transplantation in Chinese patients." (PMID 30473931, 2018). "Notably, inhibitors of the PIK3-Akt-mTOR pathway have been developed as cancer target therapy alternatives, and patients harboring PIK3CA gene mutations could be potential candidates for such therapeutic approach." (PMID 30619505, 2018). "Cancer-induced mutations and alterations of signaling pathways activate PI3K-Akt, which promotes transcriptional induction of glucose transporters [e.g., glucose transporter 1 (GLUT1)], activation of glycolytic enzymes (e.g., HK2, PFKFB3), and parallel activation of mTOR." (PMID 30123774, 2018). "Similarly, enhanced mTOR activity has been reported in cancer cell proliferation." (PMID 29491408, 2018). "Phosphoinositide 3-kinase (PI3K)-Akt-mammalian target of rapamycin inhibitor (mTOR) pathway takes part in lots of disparate cellular functions(cell growth, proliferation, autophagy, apoptosis, chemo-resistance)and has been considered as a promising drug target for cancer therapy." (PMID 29535821, 2018). "Collectively, these studies suggest that mTOR is a critical regulatory signal in the de novo purine biosynthetic pathway by influencing purinosome and mitochondria interaction and amino acid substrates, which further reprogram metabolic responses in cancer cells." (PMID 30105018, 2018). "We could not find the association of mTOR inhibitor use and risk of de novo cancer development or all-cause mortality among patients in Taiwan." (PMID 30473931, 2018).
cancer (continued). "Activation of the PI3K/Akt/mTOR signaling pathway could inhibit apoptosis induced by various stimuli and promote cell proliferation, and thus plays an important role in the initiation, development, and drug resistance of malignant tumors." (PMID 29874795, 2018). "Interestingly, Met and PI3K/Akt/mTOR pathways are simultaneously deregulated in various cancers." (PMID 30406111, 2018). "It is well known that mTOR is the switch of the autophagic pathway, which could promote cancer cell apoptosis, and mTOR activation was suppressed by TSPf, while Beclin 1, another critical molecule in autophagy, was induced, we wondered whether TSPf could trigger the autophagic process." (PMID 29997504, 2018). "For example, miR-146b-3p and miR-4433a-3p could, respectively, target NOS2 (nitric oxide synthase 2) and RPS6KB2 (ribosomal protein S6 kinase B2) of the HIF-1 signalling pathway and the mTOR signalling pathway, leading to the proliferation and invasion of cancers." (PMID 30381359, 2018). "Metformin-mediated anti-cancer activities have been associated with both systemic and cellular regulatory activities, including lowering insulin levels, increasing insulin sensitivity, and activation of AMP-activated protein kinase (AMPK)/inhibition of mammalian target of rapamycin (mTOR)." (PMID 28947975, 2017). "Although mTOR pathway inhibition is a current targeted therapy strategy, several in vitro and in vivo studies have shown that DDIT4 expression could lead to cancer progression, resistance to treatment and angiogenesis, raising an important question about the mTOR biology." (PMID 28484222, 2017). "AKAP1/mTOR signal integration on mitochondria may provide a new target for cancer therapy." (PMID 28569781, 2017). "mTORC1 is composed of mTOR, regulatory-associated protein of mTOR (Raptor), mammalian LST8/G-protein β-subunit-like protein (mLST8/GβL) and the PRAS40 and DEPTOR partners and is a master regulator of protein synthesis that couples nutrient sensing to cell growth and cancer cell survival." (PMID 29383126, 2017). "Therefore, targeting upstream signaling pathways that control mTOR may facilitate to find more sensitive targets for inhibiting cancer." (PMID 28061838, 2017). "Therefore, the present meta-analysis analyzed the associations of SNPs in the 5′upstream regulatory or promoter region (mTOR rs2295080, AKT1 rs2494752), and 3′UTR region (mTOR rs2536, pTEN rs701848 and AKT1 rs2494750) in the mTOR signaling pathway (AKT, and PTEN) with cancer risk." (PMID 29259266, 2017). "Taken together, our study suggested that the molecular mechanisms of REP1 in regulating mTOR and subsequent lysosomal degradation pathways, as well as targeting autophagy, might be possible therapeutic options for cancer patients with high expression of REP1 levels." (PMID 28846638, 2017). "In addition, the optimal dose of mTOR inhibitors for treatment of various tumors remains unknown and the failure of treatment in some cancers could be the result from the lower dose of mTOR inhibitors used in our cohort." (PMID 28160552, 2017). "Therefore, mTOR has been regarded as a crucial target for the treatment of human cancer." (PMID 28487599, 2017). "Therefore, mTOR inhibitors are being developed as potential cancer therapeutic agents." (PMID 29088817, 2017). "Notably, off-label applications of mTOR inhibitors might be successfully exploited also in non-cancer diseases." (PMID 28353628, 2017).
cancer (continued). "However, PI3K-mediated activation of downstream effectors, including the serine/threonine kinase AKT and mammalian target of rapamycin (mTOR), is key to promoting cell survival proliferation and differentiation and is aberrantly activated in a variety of human cancers." (PMID 27915408, 2017). "Given the recently reported evidence that AMPK and MTOR can indeed be concurrently activated by amino acids, we postulate that it is precisely this additional feedback action of amino acids’ provision by CAFs that stabilizes the initiation of cancer cell growth and proliferation." (PMID 28969664, 2017). "Since the number of patients with post-transplant cancers is relatively small, it is highly unlikely that a prospective, randomized trial with an adequate sample size and duration of follow-up can be performed to detect the differences of using mTOR inhibitor in these patients." (PMID 28160552, 2017). "The mTOR pathway emerges as an attractive therapeutic target in cancer because it serves as a convergence point for many growth stimuli and, through its downstream substrates, controls cellular processes that contribute to the initiation and maintenance of cancer." (PMID 28286604, 2017). "Furthermore, the Akt/mTOR pathway plays a key role in cancer cell proliferation." (PMID 29371937, 2017). "Also relevant is the recent finding that metformin’s effect as a cancer therapeutic is partially mediated by inhibition of mTOR, raising the question of whether metformin may influence the positive effects of Akt-mTOR pathway activation on muscle mass." (PMID 28270856, 2017). "Moreover, recent reports have indicated that the Akt-mTOR pathway inhibition has been confirmed to activate autophagy and suppress cancer cell growth, and the suppression of mTOR activity by rapamycin (Rapa) can induce autophagy and restrain cancer cell growth." (PMID 28891980, 2017). "Furthermore, bone colonization is induced by the osteogenic niche that is mediated by heterotypic adherens junctions including osteogenic N-cadherin and cancer-derived E-cadherin, which activate the mTOR pathway in cancer cells and consequently drive tumor progression." (PMID 29197379, 2017). "In addition, since phenformin may serve as an AMPK activator in cells with wild type LKB1, and negatively regulates mTOR activity, it is also reasonable to combine selumetinib with phenformin in cancer cells with wild type LKB1." (PMID 28938614, 2017). "Our data indicates that, under normal conditions, PML NBs play an important role in maintaining basal DDIT4 gene expression and that PML loss can lead to dysregulation of DDIT4 expression and therefore inappropriate mTOR activity that could drive cancer growth and progression." (PMID 28332630, 2017). "Importantly, 83 out of 169 cancer tissues examined contained high expression of p-mTOR, whereas 68 out of the 88 tissues containing active Skp2, supporting the conclusion that activation of mTOR signaling is involved in the overproduction of Skp2." (PMID 28446188, 2017). "Therefore, in this paper, we look into the role of ATP6v1c1 in tumor growth, and metastasis, as well as its role in mTOR signaling in both human and murine cancer cell lines to determine whether its knockdown can inhibit tumor growth." (PMID 28504970, 2017). "Given the importance of mTOR signalling in promoting cancer cell growth and proliferation and our identification of mTOR as a folate sensor, we speculate that mTOR inhibition contributes to the mechanism of action of antifolates and mTOR activation may link folate excess to carcinogenesis." (PMID 28638048, 2017). "Lactate secretion due to the over-activation of AR/PP or the augmented AKT/mTOR signaling due to AR-AKT1 interaction in cancer cells therefore might account for a significant portion of the total lactate formation, which was attributed mostly to the Warburg effects previously." (PMID 28978011, 2017).
cancer (continued). "The PI3K/Akt/mTOR signaling pathway is overexpressed or activated in various tumors and may inhibit apoptotic cell death and enhance survival and resistance to chemotherapy of cancer cells." (PMID 28785288, 2017). "Therefore, finding natural agents that suppress PI3K/AKT/mTOR signaling or induce autophagy may be a good strategy for cancer chemoprevention." (PMID 29209152, 2017). "However, the inhibition of the PI3K/Akt/mTOR pathway by small-molecule PI3K inhibitors primes cancer cells to mitochondrial apoptosis by tipping the balance toward proapoptotic Bcl-2 proteins, resulting in increased mitochondrial outer membrane permeabilization." (PMID 28959140, 2017). "However, the complex interplay between glutamine metabolism and the regulation of mTOR and autophagic processes in cancer cells makes an uncertainty whether α-KG plays a pivotal role in this respect." (PMID 28184304, 2017). "Although no overall association was identified between the activation of the mTOR pathway and the presence of functional mutations in the PIK3CA and PTEN genes, this may have been a reflection of differences between different cancer types within the limited sizes of those sample populations." (PMID 29137436, 2017). "PTEN/Akt signaling affects a wide range of cancer cell behavior, including cell viability, senescence, proliferation, migration, and invasion by regulating the activities of various transcription factors and signaling molecules, including NF-κB, β-catenin, FOXOs, and mTOR." (PMID 28030829, 2017). "Thus, as a negative regulator of mTOR, it is expected that Sestrin2 could serve as a biomarker and a therapeutic target in cancer." (PMID 28690762, 2017). "Together, MCV-positive and MCV-negative cancers may have shared abnormalities in oncogenic signaling though the underlying mechanisms are not fully understood, and targeting mTOR pathway may be therapeutic in MCC regardless of MCV status." (PMID 26536665, 2016). "ALK has also been described as rearranged or mutated in other cancer types and, in all the cases, its deregulated kinase activity leads to the activation of several downstream pathways such as MEK/ERK, STATs and AKT/mTOR, which result in abnormal proliferation and block of apoptosis." (PMID 27662658, 2016). "Surprisingly, we observed that cancer cells in the hypoxic GLUT1high, MCT4high, and mTORlow compartment were selectively depleted compared to those cells in the normoxic GLUT1low, MCT1high, and mTORhigh regions where rapamycin was acting to suppress mTOR signaling." (PMID 27134166, 2016). "On the basis of all prior observations, we hypothesized that MLL2 knockdown of a cancer cell line derived from a tumor type where MLL2 drives cancerogenesis should produce the same type of miss-regulation of the mTOR oncomodule observed in head and neck primary tumors." (PMID 27095575, 2016). "Further elucidation of the pathways by which MDSC regulate mTOR in T cells may prove essential for improving T cell responses in future therapies and for the development of treatments to overcome the suppression of T cells in patients with cancer." (PMID 27007050, 2016). "In agreement with the predictions resulting from our scoring system, the decrease in MLL2 expression, checked by quantitative PCR, resulted in increased mTORC1/2 activity, which in turn suggests that these cancer cells may be more sensitive to mTOR pathway inhibitors." (PMID 27095575, 2016). "Indeed, mutations in negative and positive regulators of mTOR signaling are among the most common tumour suppressors and oncogenes that arise in cancer patients." (PMID 26433385, 2016).
cancer (continued). "Thus, it is conceivable that a frameshift within the coding region (rs1034528) or splicing variants (rs17036508) confers hyperactivation to the mTOR protein, which promotes the development of cancer regardless of the expression level." (PMID 27462867, 2016). "Inhibition of the PI3K/Akt/mTOR pathway can effectively block the abnormal signal transduction of various growth factors leading to suppression of the occurrence and development of cancer, so it has become a hotspot of cancer prevention and cancer treatment research." (PMID 27809261, 2016). "Therefore, the mTOR pathway is highly relevant for cancer pathogenesis." (PMID 27285995, 2016). "Furthermore, because of the aberrant hyper-activation of mTOR signaling in various types of cancers, a specific inhibition by mTOR-I could represent a valuable treatment for these pathologies." (PMID 27187382, 2016). "Interestingly, deregulation of mTOR signaling has been described in many cancer types." (PMID 27293550, 2016). "Furthermore, we now show that the concomitant inhibition of mTOR and MEK promotes the apoptotic demise of HNSCC cells specifically in tumors expressing the PIK3CA oncogene, the most frequently driver mutation in this cancer type." (PMID 26882569, 2016). "Therefore, inhibiting mTOR activity would presumably prevent cancers even DNA damage accumulates." (PMID 26934328, 2016). "Thus, any medication that can prevent hyperactivation of the PI3K/Akt/mTOR signaling pathway may have the potential to act as an ovarian-protective agent and may be administered to female cancer patients for fertility preservation." (PMID 27248997, 2016). "Therefore, combination of targeting both mTOR signaling and Mnk/eIF4E pathway to enhance mTOR-targeted cancer therapy might be an innovation therapeutic strategy for NSCLC patients." (PMID 27050281, 2016). "The role of mTOR in the progression of cancer may also be related to define NF-κB11." (PMID 26892992, 2016). "Thus, mTOR can be taken as a central marker for targeted therapies aimed at human cancer cells." (PMID 27564102, 2016). "Therefore, we examined whether resveratrol-induced suppression of cancer progression occurred through mTOR and inhibition of ULK1." (PMID 26902888, 2016). "Combined ANG1/2 and mTOR blockade may have additive anti-cancer activity." (PMID 26686201, 2016). "In this context, a synergistic effect could be obtained by combining mTOR kinase inhibitors with anti-cancer drug-activating caspases, giving rise to a strong repression of the mTORC1 and thus offering new therapeutic perspectives for a large range of human diseases." (PMID 27253406, 2016). "Therefore, targeting mTOR has been proposed to be a promising approach in cancer therapy." (PMID 27137757, 2016). "In addition, those studies included cell lines from different cancer types that might have different mechanisms of PI3K/AKT/mTOR activation." (PMID 27374081, 2016). "Therefore, combining mTOR inhibitor with p38 MAPK inhibitor might have a synergetic effect on cancer cells." (PMID 29083380, 2016). "Therefore PI3K/Akt/mTOR pathway inhibitors are undergoing clinical trials for cancer treatment." (PMID 27811956, 2016). "Although the participation of key canonical pathways, such as those involving PI3K-Akt, MAPK, IGF, FGF, MET and mTOR, is well established in different cancers, these pathways cannot capture the complex and context-dependent cellular rewiring patterns behind distinct cancer phenotypes." (PMID 27527857, 2016). "Decrease the activity of the IGF-1 axis could be a desirable target for reducing cancer risk, but it is also well known that the activation of the IGF-1/AKT/mTOR (insulin-like growth factor-1/protein kinase B/mammalian target of rapamycin) pathway is one of the keys for muscular growth." (PMID 27737674, 2016). "Therefore, designing of CIP-based small molecule inhibitors to abrogate PI3K/Akt/mTOR pathway may serve as an effective therapeutic strategy to fight against various types of cancer." (PMID 27097161, 2016).